MIF (macrophage migration inhibitory factor)
Diseases named in the same sentence as MIF in open-access papers (continued):
Sharing a sentence is not in itself a finding about the gene and the disease.
primary Sjögren ́s syndrome (3 papers, 2007 to 2023). "The objective of this study was to analyse levels of the proinflammatory cytokine macrophage migration inhibitory factor (MIF) in patients with primary Sjögren's syndrome (pSS) and to examine associations of MIF with clinical, serological and immunological variables." (PMID 17470266, 2007). "Serum MIF levels are also significantly elevated in patients with primary Sjögren's syndrome, especially in those with increased γ-globulins." (PMID 22046508, 2010). "Increased production of MIF might therefore contribute to hypergammaglobulinemia and possibly reflect the disease activity of Sjögren's syndrome." (PMID 22046508, 2010). "The present study was designed to elucidate the role of MIF in primary Sjögren's syndrome (pSS)." (PMID 17470266, 2007). "Our data indicate that MIF might participate in the pathogenesis of primary Sjögren's syndrome." (PMID 17470266, 2007). "MIF was increased in serum samples from uveitis and primary Sjögren ́s syndrome patients, in ocular cicatricial pemphigoid (OCP) patients’ conjunctival samples presented increased MIF transcripts." (PMID 37626184, 2023).
proliferative diabetic retinopathy (3 papers, 2017 to 2021). Advanced retinopathy due to diabetes mellitus characterized by the formation of new vessels in the retina. "Another study reported the involvement of the MIF/CD74 signaling axis in proliferative diabetic retinopathy, suggesting that MIF expression is related to retinal neovascularization." (PMID 34445689, 2021). "We investigated the expression of MIF and its receptor CD74 in proliferative diabetic retinopathy (PDR) to reveal a possible role of this pathway in the pathogenesis of PDR." (PMID 31866994, 2019). "Comparisons of migration inhibitory factor (MIF), vascular endothelial growth factor (VEGF) and soluble intercellular adhesion molecule-1 (sICAM-1) in vitreous samples from patients with proliferative diabetic retinopathy (PDR) and nondiabetic patients with rhegmatogenous retinal detachment (RD)." (PMID 31866994, 2019).
proliferative glomerulonephritis (3 papers, 2015 to 2022). A constellation of renal disorders characterized by an increase number of cells in the glomerulus; these disorders generally present with nephrotic syndrome, and generally progress to end stage renal failure over a matter of weeks to years, depending on the etiology. "Increased MIF locally produced and secreted in damaged kidneys could be associated with a progressive increased production of MIF in proliferative glomerulonephritis, according to the immunohistochemical staining and measurement of urinary MIF concentrations." (PMID 36329091, 2022). "MIF urinary excretion appears to be a prognostic marker of therapy outcomes only in proliferative glomerulonephritis, in which lower urinary MIF may be linked with good prognosis, whereas a higher MIF urinary excretion value was a marker of unfavorable therapy outcomes." (PMID 26272322, 2015). "A number of scholars have found that the urinary MIF concentration significantly increases in proliferative glomerulonephritis, and urinary MIF level reflects MIF expression within the kidney in crescentic GN, particularly in disease exacerbation." (PMID 36329091, 2022). "Some scholars demonstrated the expression of MIF protein in kidney tissue of human proliferative glomerulonephritis, and this was correlated with leukocyte infiltration, histologic damage, and renal function impairment." (PMID 36329091, 2022). "In contrast, in proliferative glomerulonephritis, the urinary excretion of MIF was significantly higher in the NR than the R subgroup." (PMID 26272322, 2015). "Furthermore, a previous study demonstrated that urinary excretion of MIF could be a prognostic marker only in proliferative glomerulonephritis, accompanying with higher values related to a worse prognosis." (PMID 36329091, 2022).
Psoriasiform dermatitis (3 papers, 2018 to 2025). A skin abnormality characterized by redness and irritation, with thick, red skin that displays flaky, silver-white patches (scales). "Deficiency in MIF significantly blunts psoriasiform dermatitis in both models, suggesting that MIF possibly acts as effector molecule downstream of IL-23." (PMID 30333830, 2018). "The immunomodulator Macrophage Migration Inhibitory Factor (MIF) has also been identified as a potential driver of psoriasiform dermatitis." (PMID 40724528, 2025). "Elevated in the skin and serum of psoriasis patients, MIF expression is further upregulated in mouse models of psoriasiform dermatitis induced by imiquimod and IL-23." (PMID 40724528, 2025). "In MIF-null mice, severity of psoriasiform dermatitis was lower and macrophage recruitment was impaired." (PMID 35837394, 2022). "Our more detailed investigation reveals that MIF is involved in orchestrating the recruitment of monocytes into the dermis, which has lately been highlighted as crucial for the emergence of psoriasiform dermatitis in both models." (PMID 30333830, 2018). "This indicates that MIF directly or indirectly promotes the uncontrolled proliferation of keratinocytes in psoriasiform dermatitis." (PMID 30333830, 2018). "To identify potential cellular sources of MIF in IIPD, we assayed MIF expression at the mRNA and protein level in psoriasiform dermatitis by qPCR and immunofluorescence staining, respectively." (PMID 30333830, 2018). "Disease severity was equivalent in wild-type → wild-type and Mif−/− → wild-type chimera, but was decreased in wild-type → Mif−/− and Mif−/− → Mif−/− chimera when compared to the first two groups, indicating specifically that MIF derived from radioresistant cells aggravates psoriasiform dermatitis." (PMID 30333830, 2018). "As a corollary, MIF may promote psoriasiform dermatitis in the IIPD model by facilitating monocyte recruitment into the dermis." (PMID 30333830, 2018).
psoriatic arthritis (3 papers, 2015 to 2021). Joint inflammation associated with psoriasis. "Conversely, for −794 CATT5–8 MIF polymorphism, the 5,6 genotype was the most frequent in a Japanese population and, for the SNP −173 G>C, the C allele was the most frequent in Caucasian patients with psoriatic arthritis." (PMID 25972622, 2015).
thyroid cancer (3 papers, 2017 to 2022). "We have previously shown that inhibition of MIF/CD74 signalling axis blocks thyroid cancer cells growth by inducing cell death during mitosis." (PMID 28114961, 2017). "Based on these studies, the signaling pathway that UHRF1 plus c-Jun/AP-1 increased the expression of IL-6 and MIF might be a potential key mechanism of thyroid cancer metastasis." (PMID 35996525, 2022). "To study how UHRF1 promoted thyroid cancer cell metastasis, we analyzed the transcription levels of key regulators of immunoregulatory cytokine interleukin 6 (IL-6) and the macrophage migration inhibitory factor (MIF) in BCPAP by qPCR." (PMID 35996525, 2022). "Our results suggest that UHRF1 could induce the metastasis of thyroid cancer, and the potential signaling pathway might be that UHRF1 activates c-Jun/AP-1 to increase the expression of IL-6 and MIF." (PMID 35996525, 2022).
trypanosomiasis (3 papers, 2013 to 2017). Infection with protozoa of the genus trypanosoma. "While there are no human studies directly linking MIF to HAT, murine studies show that MIF plays a role as a mediator of the inflammation which is a key feature in trypanosomiasis-associated pathology." (PMID 29059176, 2017). "Our experiments uncovered that macrophage migration inhibitory factor (MIF) plays a pivotal role in trypanosomiasis-associated pathogenicity development." (PMID 25255103, 2014). "The current findings therefore offer promise for human translation and open the possibility of assessing MIF levels or MIF genotype as an indication of an individual's risk for severe trypanosomiasis." (PMID 25255103, 2014). "Moreover, low-expression MIF alleles, which occur more commonly in Africans, may offer protection from disease manifestations in trypanosomiasis endemic settings." (PMID 25255103, 2014). "Since the transfer of neutrophils from Mif−/− mice into WT recipient mice did not affect TNF and liver injury, it seems that MIF production by neutrophils evidenced in this report plays a prominent, previously unappreciated role in trypanosomiasis-associated pathogenicity." (PMID 25255103, 2014).
Ureteral obstruction (3 papers, 2015 to 2022). Obstruction of the flow of urine through the ureter. "In mice with unilateral ureteral obstruction, gene deletion or pharmacological inhibition of MIF aggravates fibrosis and inflammation, even after fibrosis has occurred, treatment with recombinant MIF can still provide protection." (PMID 36117692, 2022). "However, MIF absence from mice did not protect from renal allograft rejection or ureteral obstruction-induced kidney injury." (PMID 26441987, 2015).
Venous thrombosis (3 papers, 2011 to 2022). Formation of a blood clot (thrombus) inside a vein, causing the obstruction of blood flow. "MIF levels in plasma and urine could reflect the severity of MN, and MIF levels in plasma and urine could be associated with venous thrombosis and infectious complications in MN patients." (PMID 36329091, 2022). "In conclusion, plasma and urinary MIF levels could reflect the severity of MN, and they could be associated with venous thrombosis and infectious complications in MN patients." (PMID 36329091, 2022).
adenomyosis (2 papers, 2020 to 2025). The growth of endometrial tissue inside the muscular wall of the uterine corpus. "In our data analysis results, we also found MIF to be significantly differentially expressed in the endometrium of women with adenomyosis." (PMID 32719721, 2020). "Thus, MIF may be involved in endometrial dysfunction of women with adenomyosis, but not under the regulation of m6A RNA methylation regulators." (PMID 32719721, 2020).
Adrenal insufficiency (2 papers, 2009 to 2013). Insufficient production of steroid hormones (primarily cortisol) by the adrenal glands. "An inflammatory imbalance involving GC and MIF might be the cause or result of adrenal insufficiency." (PMID 20021698, 2009). "In the present study, we focused on macrophage migration inhibitory factor (MIF) as an indicator of adrenal insufficiency." (PMID 20021698, 2009). "As a result, we could determine the threshold serum MIF level that defines adrenal insufficiency." (PMID 20021698, 2009). "Six-month DHEAS treatment in women with adrenal insufficiency did not affect MCP-1 levels despite increased LBM, but fat distribution was unchanged and MIF data were not available in the study." (PMID 24089589, 2013).
alcohol use disorder (2 papers, 2021 to 2023). "Ibudilast, a neuroimmune modulator which selectively inhibits phosphodiesterases (PDE)-3, -4, -10, and -11, and macrophage migration inhibitory factor (MIF), shows promise as a novel pharmacotherapy for alcohol use disorder (AUD)." (PMID 34120149, 2021).
alcoholic cirrhosis (2 papers, 2021 to 2022). "Simultaneously, levels of macrophage migration inhibitory factor (MIF) and inflammatory cytokines are amplified in alcoholic cirrhosis patients, though the exact mechanism of MIF increase is unknown." (PMID 35633655, 2022).
allergic conjunctivitis (2 papers, 2015 to 2023). "Further, MIF protein levels were significantly higher in lacrimal fluid from allergic conjunctivitis than healthy individuals." (PMID 37626184, 2023). "In contrary, mice engineered to over-express MIF protein (MIF-transgenic mice), presented worsened outcome of allergic conjunctivitis as compared to WT and MIF KO mice." (PMID 37626184, 2023). "It was demonstrated, the tear MIF concentration was significantly higher in patients with severe AD and patients with allergic conjunctivitis than in healthy controls." (PMID 25647395, 2015). "Therefore, targeted inhibition of MIF might result as a new option to control pollen-induced allergic conjunctivitis and pollen dermatitis." (PMID 25647395, 2015). "Therefore, the targeted inhibition of MIF might result as a new option to control pollen-induced allergic conjunctivitis and pollen dermatitis." (PMID 25647395, 2015).
allergic disease (2 papers, 2022 to 2024). An immune response that occurs following re-exposure to an innocuous antigen, and that requires the presence of existing antibodies against that antigen. "Trx1 plays an important role in allergic diseases through processes, such as antioxidation, inhibiting macrophage migration inhibitory factor (MIF), regulating Th1/Th2 immune balance, modulating allergic inflammatory cells, and suppressing complement activation." (PMID 35572600, 2022). "Previously, in allergic reactions, increased mRNA expression of different proteins, namely, the chemokine interferon-γ-inducible protein-10 (CXCL10) and the related CXC chemokine receptor 3-activating chemokines (CXCR3) macrophage migration inhibitory factor (MIF) and IP-9, was identified." (PMID 39062959, 2024).
bacterial meningitis (2 papers, 2009 to 2021). Inflammation of the membranes surrounding the brain and spinal cord due to a bacterial infection. "We found that higher plasma MIF concentrations during the early phase of disease were predictive for mortality in bacterial meningitis." (PMID 33407905, 2021). "Our study shows that high MIF concentrations in the early phase of acute bacterial meningitis predict poor outcome of disease." (PMID 33407905, 2021). "Anti-inflammatory therapy with corticosteroids is beneficial in bacterial meningitis, suggesting that MIF may also influence the course of central nervous system (CNS) infections." (PMID 19558639, 2009).
bone cancer (2 papers, 2022 to 2024). A primary or metastatic malignant neoplasm affecting the bone or articular cartilage. "Altogether, these findings suggest that the clearance of apoptotic cancer cells by BM macrophages triggers p-STAT3/HIF-1α/MIF signaling to promote further inflammation in the bone tumor microenvironment where a significant number of apoptotic cancer cells are present." (PMID 36496973, 2022). "Altogether, these results suggest that STAT3–HIF-1α–MIF is a potent signaling axis induced by BM macrophage efferocytosis of apoptotic cancer cells, which may act via paracrine signaling to induce macrophage-mediated inflammation in the bone tumor milieu." (PMID 36496973, 2022). "This is interesting in light of our current results showing increased NEEP21 levels after persistent BHA and reversal with spinal anti-MIF treatment, as spinal ERK activation mediates bone cancer pain in a rodent model." (PMID 38674069, 2024).
cataract (2 papers, 2023). Partial or complete opacity of the crystalline lens of one or both eyes that decreases visual acuity and eventually results in blindness. "The increase in MIF mRNA abundance in the lenses of cataract rats is affiliated with the proliferation of undifferentiated epithelial cells." (PMID 36586009, 2023).
central nervous system infection (2 papers, 2009 to 2020). "Macrophage migration inhibitory factor (MIF) plays an essential pathophysiological role in septic shock, but its role in central nervous system infection (CNS) remains to be defined." (PMID 19558639, 2009).
chondrosarcoma (2 papers, 2013 to 2017). A malignant cartilaginous matrix-producing mesenchymal neoplasm arising from the bone and soft tissue. "Meanwhile, FGF2 has been reported to regulate MMP-13 expression with a time- and dose-dependent relation in chondrosarcoma cells, leading to the degradation of extracellular migration inhibitory factor (MIF) to promote cancer metastasis." (PMID 28740507, 2017). "Macrophage migration-inhibitory factor (MIF), a pro-inflammatory cytokine involved in macrophage migration and activation, is able to enhance the migration of chondrosarcoma cells by increasing αvβ3 integrin expression, mediated via PI3K/Akt/NF-κB signaling." (PMID 24490159, 2013).
co-infection (2 papers, 2016 to 2025). "Cytokine array analysis revealed that KSHV co-infection induces the production of several inflammatory cytokines and chemokines, including MIF, in SiHa cells." (PMID 41472252, 2025). "Furthermore, our data show that KSHV co-infection upregulates MIF and its receptors (e.g., CD74, CXCR2, CXCR4) both in vitro and in vivo." (PMID 41472252, 2025).
congenital diaphragmatic hernia (2 papers, 2018 to 2023). A posterolateral defect of the diaphragm that allows passage of abdominal viscera into the thorax, leading to respiratory insufficiency and persistent pulmonary hypertension with high mortality. "Macrophage migration inhibitory factor (MIF) was reported to upregulate sFLT1 production in experimental congenital diaphragmatic hernia." (PMID 37373198, 2023). "Additionally, it has been shown that MIF increases sFLT1 production in experimental congenital diaphragmatic hernia." (PMID 37373198, 2023).
congenital heart disease (2 papers, 2010 to 2019). A heart disease that is present at birth. "Previously, we demonstrated that serum MIF is increased in pediatric PHT associated with congenital heart disease (CHD)." (PMID 30881226, 2019). "Plasma MIF increased significantly in pediatric patients undergoing surgery for congenital heart disease." (PMID 21197406, 2010).
cutaneous squamous cell carcinoma (2 papers, 2023). "Our previous study revealed an enhanced expression of MIF in lesional skin of patients with actinic keratosis or cutaneous squamous cell carcinoma (SCC), together pointing towards an important role for MIF in the pathogenesis of NMSC3." (PMID 37464010, 2023).
delirium (2 papers, 2020). A disorder characterized by confusion; inattentiveness; disorientation; illusions; hallucinations; agitation; and in some instances autonomic nervous system overactivity. "Removal of MIF may have a protective effect on the central nervous system and reduce the incidence of postoperative delirium." (PMID 33228727, 2020).
diabetic cardiomyopathy (2 papers, 2011 to 2019). Diabetic cardiomyopathy is a disorder of the heart muscle in people with diabetes. "The purpose of this study was to examine the expression levels of macrophage migration inhibitory factor (MIF) and G protein-coupled receptor kinase 2 (GRK2) in patients with early diabetic cardiomyopathy, and to investigate the mechanisms involved in MIF expression and GRK2 activation." (PMID 21283592, 2011). "However, the role of MIF in diabetic cardiomyopathy has not been studied in vivo and the signaling pathways mediating MIF's effect remains unknown." (PMID 21283592, 2011).
diffuse systemic sclerosis (2 papers, 2018 to 2022). "In accordance with this notion, the MIF rs755622*C allele was associated with susceptibility to PH in diffuse systemic sclerosis." (PMID 30567353, 2018).
disc degeneration (2 papers, 2021 to 2025). "Hence, more researches on the MIF-associated biological changes in the pathomechanism of disc degeneration will be exerted in our further studies." (PMID 34306312, 2021). "Our findings provide a better understanding of the regulatory role of mechanical compression on the cellular fate commitment and matrix metabolism of NP, and the potential strategies for treating disc degenerative diseases via using MIF-regulating agents." (PMID 34306312, 2021). "This work helps us better understand the regulating function of mechanical compression stress in the progress of disc degeneration and provides more substantial proofs for using MIF-alerting agents in treating disc degenerative diseases." (PMID 34306312, 2021). "Second, the mechanism behind ROS-induced MIF release remains elusive, and the current study simply focused on its autophagy-inducing role involved in the progress of mechanical compression-related disc degeneration." (PMID 34306312, 2021).